SNHG4 (small nucleolar RNA host gene 4)
Synonyms: U19H; NCRNA00059
Gene: Long non-coding RNA gene on chromosome 5 (139,274,102 to 139,284,899, forward strand). Ensembl gene ENSG00000281398.
Diseases named in the same sentence as SNHG4 in open-access papers:
SNHG4 is named in the same sentence as 37 diseases in open-access papers, as found by Europe PMC text mining. Sharing a sentence is not in itself a finding about the gene and the disease. The quoted sentences say what the papers report.
prostate carcinoma (12 papers, 2020 to 2026). A carcinoma that arises from epithelial cells of the prostate gland. "RREB1 promotes prostate cancer by activating the transcription of SNHG4, which promotes DNA damage repair, the cell cycle, and resistance to the androgen-receptor antagonist enzalutamide." (PMID 41516419, 2026). "Small nucleolar RNA host gene 4 (SNHG4) has been a research hotspot in tumor-related diseases, especially in prostate cancer, lung cancer, and human osteosarcoma." (PMID 39735673, 2025). "We further analyzed the prognostic role of SNHG4 in prostate cancer, and survival analysis suggested that high SNHG4 expression was correlated with poor OS (HR = 6.64, p = 0.035) and PFI (HR = 2.09, p < 0.001) in PCa patients." (PMID 37596700, 2023). "We assumed that SNHG4 facilitates prostate cancer cell proliferation, the cell cycle and senescence by regulating RRM2, EZH2, AURKA and TK1." (PMID 37596700, 2023). "To examine the role of SNHG4 in prostate cancer, we used TCGA databases to analyze the expression patterns of SNHG4 between the normal group (n = 52) and tumor group (n = 499) and subgroups of PCa." (PMID 37596700, 2023). "To evaluate the location of SNHG4 in prostate cancer cells, we performed an immunofluorescence assay using 22Rv1 and LNCaP cells." (PMID 37596700, 2023). "As we have identified SNHG4-let-7 miRNA-RRM2 regulation in prostate cancer, we then sought to evaluate the prognostic role and biological functions of SNHG4 in PCa." (PMID 37596700, 2023). "Our study revealed the prognostic value and biological functions of SNHG4 in stimulating prostate cancer progression." (PMID 37596700, 2023). "The results from TCGA databases and our cohort supported an oncogenic role of SNHG4 in prostate cancer progression." (PMID 37596700, 2023). "In this study, we identified novel functions of the lncRNA SNHG4 in driving prostate cancer progression and enzalutamide resistance." (PMID 37596700, 2023). "Our study uncovered a novel molecular mechanism of lncRNA SNHG4 in driving prostate cancer progression and enzalutamide resistance, revealing the critical roles and therapeutic potential of RREB1, SNHG4, RRM2 and let-7 miRNAs in anticancer therapy." (PMID 37596700, 2023). "Overall, our study outlined the significant prognostic value of high SNHG4 expression in prostate cancer and the novel mechanisms by which SNHG4 drives prostate cancer progression and drug resistance." (PMID 37596700, 2023). "The results suggested that high expression of SNHG4 was correlated with RRM2/EZH2/AURKA/TK1 overexpression in prostate cancer tissue specimens." (PMID 37596700, 2023). "Elevated lncRNA SNHG4 expression has been detected in prostate cancer, while depleted lncRNA SNHG4 has been demonstrated to suppress prostate cancer cell growth, migration, and invasion." (PMID 33816782, 2021). "In prostate cancer, SNHG4 relieved the miR-377-induced suppression of ZIC5 by acting as a ceRNA, therefore promoting ZIC5-mediated growth and metastasis." (PMID 33744866, 2021). "Among these SNHGs, aberrant expression of SNHG4, located in 5q31.2, has been reported in various human malignancies, such as prostate cancer, osteosarcoma, cervical cancer, and hepatocellular carcinoma." (PMID 33088220, 2020). "Recently, dysregulation of SNHG4 has been found in various human malignancies, such as prostate cancer, osteosarcoma, cervical cancer, and hepatocellular carcinoma." (PMID 33088220, 2020). "Next, we aimed to construct a regulatory loop that may constitutively activate the transcription of SNHG4 in prostate cancer." (PMID 37596700, 2023). "In addition, SNHG4 was found to be upregulated in prostate cancer tissues and mechanistically promotes prostate cancer cell growth and metastasis by acting as a ceRNA and interacting with miR-377." (PMID 37596700, 2023).
prostate carcinoma (continued). "Third, let-7 has been recognized to regulate the CSC phenotypes of human cancers, and since we have proven that SNHG4 sponges let-7, whether SNHG4 affects the stemness of prostate cancer is worthy of investigation." (PMID 37596700, 2023). "In this study, for the first time, we uncovered the mechanisms by which SNHG4 facilitates the survival of PCa cells and resistance to enzalutamide, and we investigated a positive feedback loop that may enhance the overexpression of SNHG4 in prostate cancer." (PMID 37596700, 2023). "In prostate cancer, SNHG4 is reported to sponge miR-377 and regulate ZIC expression." (PMID 37596700, 2023). "SNHG4 enhanced osteosarcoma, cervical cancer and prostate cancer." (PMID 33333852, 2020). "The RREB1/SNHG4/let-7a regulatory loop may enhance the aggressiveness of prostate cancer." (PMID 37596700, 2023). "Therefore, we hypothesized that RREB1 transcriptionally regulates SNHG4 expression in prostate cancer." (PMID 37596700, 2023). "Thus, we aimed to investigate whether depletion of SNHG4, RRM2, EZH2, AURKA or TK1 can cause prostate cancer cell senescence and affect cell viability." (PMID 37596700, 2023). "Regarding transcription factor-driven and signaling pathway activation, SNHG4 is overexpressed under the regulation of SP1, promoting prostate cancer cell proliferation, migration, and invasion by sponging miR-377 to upregulate the oncogene ZIC5." (PMID 41301542, 2025). "Our study uncovered a novel molecular mechanism of lncRNA SNHG4 in driving prostate cancer progression and enzalutamide resistance, revealing the critical roles and therapeutic potential of RREB1, SNHG4 and let-7 miRNAs in anticancer therapy." (PMID 37596700, 2023). "In the previous studies, SNHG4, as a miR-377 sponge, was demonstrated to elevate the expression of ZIC5 in prostate carcinoma." (PMID 33088220, 2020). "In prostate cancer, SNHG6 modulates cancer cell sensitivity to paclitaxel by sponging miR-186, SNHG12 influences tumorigenesis through targeting miR-133b, and SNHG4 enhances ZIC5-mediated tumor growth and metastasis via the regulation of miR-377." (PMID 41301542, 2025). "In addition, numerous lncRNAs have been reported to regulate the sensitivity of cancer cells to the cytotoxicity of tumor-reactive T cells, such as SNHG4 or MALAT1 in diffuse large B cell lymphoma, and KCNQ1OT1 in prostate cancer." (PMID 36482354, 2022). "The role of C6orf223 and NSUN5P1 in cancer has not yet been reported, but many studies have shown that SNHG4 is involved in multiple cancers, including osteosarcoma, prostate cancer, and cervical cancer." (PMID 33744866, 2021).
osteosarcoma (11 papers, 2020 to 2025). A usually aggressive malignant bone-forming mesenchymal neoplasm, predominantly affecting adolescents and young adults. "In addition, high expression of SNHG4 was associated with lung metastasis in neuroblastoma, lymph node metastasis in PCa, and distant metastasis in osteosarcoma." (PMID 34717631, 2021). "Furthermore, in osteosarcoma cell lines, the SNHG4/miR-224-3p/DOCK7 axis was implicated in the regulation of cell proliferation, migration, and invasion." (PMID 33088220, 2020). "In contrast, miR-224-3p abolishes the tumour-promoting effects of the lncRNA small nucleolar RNA host gene 4 (SNHG4) in osteosarcoma." (PMID 34893064, 2021). "Researchers used TCGA RNA-seq data to evaluate the expression of SNHG4 in human osteosarcoma samples." (PMID 34717631, 2021). "Previously, it has been shown that lncRNA SNHG4 can promote osteosarcoma growth via sponging miR-224-3p, which can predict a poor survival and recurrence." (PMID 32454787, 2020). "Lnc SNHG4: Lnc-RNA small nucleolar RNA host gene 4 (SNHG4) was recently identified in osteosarcoma." (PMID 37762249, 2023). "In addition, they pointed out that a high level of SNHG4 is closely related to advanced pathological stage (P = 0.036) and distant metastasis (P = 0.039) in osteosarcoma patients." (PMID 34717631, 2021). "SNHG4 boosts osteosarcoma growth by competitively binding miR-224-3p." (PMID 33088220, 2020). "SNHG4 boosts osteosarcoma advancement by competitively binding miR-224-3p." (PMID 33088220, 2020). "In osteosarcoma, SNHG4 expression was remarkably elevated, and high SNHG4 expression was correlated with larger tumor size and impaired prognosis of osteosarcoma patients; regarding the molecular mechanism, SNHG4 exerted oncogenic effects in osteosarcoma by sponging miR-224-3p." (PMID 33744866, 2021). "Among the prognosis-related lncRNAs in HCC, SNHG3, SNHG4, and NRAV have been reported to function in bladder cancer, non-small cell lung cancer, osteosarcoma, colorectal cancer, breast cancer, gastric cancer, and glioma through interactive molecular pathway studies." (PMID 35734590, 2022). "Similarly, SNHG4 knockdown could inhibit RCC, CRC, osteosarcoma, CC, lung cancer, and NSCLC tumour growth." (PMID 34717631, 2021).
lung cancer (9 papers, 2020 to 2025). A malignant neoplasm involving the lung. "It was reported that SNHG4 promoted the progression of non‐small cell lung cancer (NSCLC) via modulating microRNA‐let‐7 e/KDM3A/p21 pathway." (PMID 36565037, 2023). "SNHG4 is a well-known oncogene and participates in a variety of mechanisms to enhance tumor progression, such as in colorectal cancer and lung cancer." (PMID 37596700, 2023). "In GC, neuroblastoma, and lung cancer, it has been reported that SNHG4 promotes EMT by upregulating E-cadherin and downregulating N-cadherin, thereby exerting a tumorigenic effect." (PMID 34717631, 2021). "LINC00942, LINC01116, SNHG4, MIR31HG, and LINC00460 had been known to be associated with tumor development and progression and drug resistance in various cancers including lung cancer." (PMID 35083132, 2021). "In lung cancer, Tang and colleagues found that SNHG4 promotes cell growth by increasing the protein levels of Ki67, CDK4 and CDK6." (PMID 34717631, 2021). "Studies have found abnormal expression of SNHG4 in many diseases, for example, decreased expression in diabetic retinopathy and acute myeloid leukemia, while increased expression in endometriosis, gastric cancer, neuroblastoma and lung cancer." (PMID 38114929, 2023). "Previous literature studies have demonstrated the protective effect of SNHG4 in lung cancer and LPS-induced inflammatory lung injury, so we have reason to speculate that SNHG4 may be related to the occurrence of COPD." (PMID 38114929, 2023). "Notably, lncRNA SNHG4 has been reported to promote the metastasis of lung cancer cells, while the impact of lncRNA SNHG4 on NSCLC and its downstream mechanism remains largely unclear." (PMID 33816782, 2021). "In addition, a recent study suggested that lncRNA SNHG4 regulates the development of lung cancer via miR-98-5p." (PMID 33816782, 2021). "Similarly, lncRNA SNHG4 has been reported to be upregulated in lung cancer cells, while the silencing of lncRNA SNHG4 plays a contributory role in the inhibition of lung cancer progression in vitro and in vivo." (PMID 33816782, 2021). "In addition, lncRNAs such as DANCR, LINC00336, MNX1-AS1, LINC00673, SNHG4, LEF1-AS1, UCA1 (urothelial carcinoma-associated 1), SNHG1, and PTAR act as ceRNAs for miRNAs and exhibit oncogenic functions in lung cancer cells." (PMID 33412752, 2020). "SNHG4 acted as a sponge for miR-98-5p, which can directly target CDK6 and SALL4, and SALL4 is upregulated in lung cancer tissues." (PMID 33412752, 2020). "SNHG4 is not described for HNSCC, but in lung cancers it affects proliferation, migration and invasiveness, as well as EMT through miR-98-5p." (PMID 32947877, 2020).
colorectal cancer (8 papers, 2021 to 2025). A primary or metastatic malignant neoplasm that affects the colon or rectum. "For example, SNHG4 was expressed highly in colorectal cancer, and promotes apoptosis of CD4+ T cells through a miRNA sponge binding to miR-144-3p and competing with the MET oncogene." (PMID 41154428, 2025). "In colorectal cancer, SNHG4 promoted the cellular proliferation via accelerating cell cycle through regulating miR‐590‐3p/CDK1 axis." (PMID 36565037, 2023). "SNHG4 has been reported to play an oncogenic role in many cancer types, including non-small cell lung cancer, colorectal cancer, and cervical cancer." (PMID 37596700, 2023). "Likewise, SNHG4 accelerates colorectal cancer cell cycle and cell proliferation." (PMID 39735673, 2025).
cervical cancer (7 papers, 2020 to 2023). A primary or metastatic malignant neoplasm involving the cervix. "Using a xenograft mouse model, the functional role of SNHG4 has been studied in gastric, prostate, cervical cancer, and endometriosis." (PMID 37189636, 2023). "In cervical cancer, SNHG4 serves as a ceRNA for miR-148a-3p, thereby upregulating the expression of the miR-148a-3p downstream target c-Met and ultimately promoting the development of cervical cancer." (PMID 33744866, 2021). "In addition, SNHG4 can promote cervical cancer progression via regulating miR-206 and YWHAZ." (PMID 32454787, 2020). "In ACI, NP, DR, AML, neuroblastoma, CRC, cervical cancer (CC), non-small-cell lung cancer (NSCLC), and endometriosis, researchers explored the expression of SNHG4 in patients with these diseases." (PMID 34717631, 2021).
gastric cancer (7 papers, 2019 to 2025). A primary or metastatic malignant neoplasm involving the stomach. "Especially, it was reported that SNHG4 enhanced the EMT process through sponging miR‐204‐5p in gastric cancer." (PMID 36565037, 2023). "An example is SNHG4 miR-204-5p sponges; they increase the expression of RRM2 which causes the occurrence of gastric cancer." (PMID 36672893, 2023). "The expression of SNHG4 and LINC00523 was up-regulated in gastric cancer." (PMID 30430424, 2019).
liver cancer (7 papers, 2020 to 2025). An epithelial or non-epithelial malignant neoplasm that arises from the liver. "Other published research uncovered that lncRNA SNHG4 was highly expressed in liver cancer tissues compared to normal liver tissues; moreover, the expression of lncRNA SNHG4 was associated with OS." (PMID 36761763, 2023). "Although SNHG4 has been reported to be highly expressed in liver cancer and associated with prognosis, the definite molecular functions of lncRNA SNHG4 in HCC remain uncertain." (PMID 36565037, 2023). "After pathway enrichment analysis in the TCGA-LIHC cohort, SNHG4 was found to be closely associated with liver cancer progression." (PMID 35686101, 2022). "The results of our study have shown that the up-regulation of SNHG4 expression is associated with poor survival and has an independent prognostic role in liver cancer." (PMID 31967298, 2020). "In HCC cell lines, SNHG3 overexpression promotes the proliferation, migration, and EMT, and inhibits apoptosis, while higher levels of SNHG4 are more likely to indicate poor prognosis in liver cancer." (PMID 35754846, 2022). "Multivariate analysis further identified SNHG4 as an independent prognostic factor of poor survival in liver cancer." (PMID 34717631, 2021). "SNHG4 expression was significantly higher in liver cancer tissues (n = 371; P < 0.05) compared with normal liver tissues (n = 50), which was validated by HCCDB database." (PMID 31967298, 2020). "Further multivariate analysis determined the independent prognostic value of high SNHG4 expression for poor overall survival of liver cancer (hazard ratio: 2.84, 95% confidence interval: 1.90–4.23, P < 0.001)." (PMID 31967298, 2020). "Further multivariate analysis determined the independent prognostic value of high SNHG4 expression for poor relapse-free survival of liver cancer (hazard ratio: 1.95, 95% confidence interval: 1.29–2.94, P = 0.002)." (PMID 31967298, 2020). "In the present study, we found the higher SNHG4 expression in liver cancer, and the relationship between SNHG4 expression and histological type, histologic grade, stage, T classification, and survival status." (PMID 31967298, 2020). "Multivariate analysis identified SNHG4 as an independent prognostic factor of poor survival in liver cancer." (PMID 31967298, 2020). "In the present study, we explored the SNHG4 expression in liver cancer and compared the relationship between SNHG4 expression and clinical parameters." (PMID 31967298, 2020). "In the present study, we also made the same conclusion that SNHG4 expression is an independent predictor of poor prognosis in liver cancer." (PMID 31967298, 2020). "Here, we focused on the small nucleolar RNA host gene 4 (SNHG4) in liver cancer prognosis based on The Cancer Genome Atlas (TCGA) data." (PMID 31967298, 2020). "High SNHG4 expression is an independent predictor of poor prognosis in liver cancer." (PMID 39735673, 2025). "Researchers have discussed the role of SNHG4 in liver cancer." (PMID 34717631, 2021). "The patients with liver cancer were divided into high and low SNHG4 expression groups." (PMID 31967298, 2020). "Our study provides a new insight that SNHG4 played a valuable role in the prognosis of liver cancer, which may have an influence on the signaling pathway and laid a foundation for further studies to explore the SNHG4-related ceRNA mechanisms in deep." (PMID 31967298, 2020). "To identify SNHG4-related signaling pathway activated in liver cancer, we conducted the GSEA between low and high SNHG4 expression data sets." (PMID 31967298, 2020). "However, the prognostic role and potential mechanism of SNHG4 in liver cancer remain unclear." (PMID 31967298, 2020). "However, there are not enough studies on the effect of SNHG4 on liver cancer, and we used a cell assay to analyze the impact of SNHG4 in liver cell carcinoma." (PMID 35686101, 2022).
hepatocellular carcinoma (6 papers, 2020 to 2023). A malignant tumor that arises from hepatocytes. "Moreover, SNHG4 expression was shown to be dramatically upregulated in hepatocellular carcinoma, and SNHG4 upregulation independently predicted lower overall survival of hepatocellular carcinoma patients." (PMID 33744866, 2021). "The data concerning hepatocellular carcinoma (HCC) from The Cancer Genome Atlas (TCGA) was analyzed to identify the expression level of SNHG4, and both unpaired and paired analysis results displayed that the expression of SNHG4 in HCC tissues was notably higher than that in normal tissues." (PMID 36565037, 2023). "For example, Chen found that SNHG8 overexpressed in non-small cell lung carcinoma (NSCLC), and Dong found that SNHG8 is an oncogene in human hepatocellular carcinoma, Meng found SNHG6 promotes glioma tumorigenesis in glioma, and Zhu found SNHG4 overexpressed in hepatocellular carcinoma." (PMID 31967298, 2020).